MT1G (metallothionein 1G)
Diseases named in the same sentence as MT1G in open-access papers (continued):
Sharing a sentence is not in itself a finding about the gene and the disease.
tumor (67 papers, 2004 to 2025). "Our results firstly confirmed our previous observation: MT1G is significantly downregulated in tumoral tissue and the downregulatory extent of MT1G is significantly associated with tumor size and poor prognosis." (PMID 31732712, 2019). "Hypermethylation of MT1G is associated with the higher stage of tumor in EC." (PMID 34531924, 2021). "Hematoxylin-eosin (HE) staining and IHC results showed that MT1G overexpression correlated with increased expression of Ki67, N-cadherin, and Vimentin, as well as decreased E-cadherin expression in xenograft tumor cells." (PMID 38906969, 2024). "During these 26 days, the tumor volumes were measured and immunohistochemistry (IHC) analysis of tumor tissues using MT1G, Ki67, E-cadherin, and N-cadherin antibodies were performed." (PMID 38906969, 2024). "In this study, we screened 19 genes associated with ferroptosis, of which 10 FerDEGs such as TLR4, KRAS and HSF1 were highly expressed and 9 FerDEGs such as MUC1, PROM2 and MT1G were lowly expressed in tumour tissue." (PMID 36936437, 2023). "The results showed that MT1G was significantly downregulated in tumor tissues at both the mRNA and protein levels." (PMID 36204178, 2022). "Alternatively, when further analyzing the correlation between MT1G expression and the clinicopathological factors in ccRCC patients, we found that MT1G was upregulated in tissues with a higher degree of malignancy and advanced tumor stage." (PMID 36204178, 2022). "By comparing MT1G expression levels in ccRCC tumor samples and normal kidney samples, it was found that MT1G was significantly downregulated in tumor tissues (p < 0.01)." (PMID 36204178, 2022). "Emerging evidence suggests the crucial role of metallothioneins (MTs), including MT1G, in tumor formation, progression, and drug resistance." (PMID 36439512, 2022). "On the other hand, some studies have shown that high expression of MT1G is a prognostic factor for tumor progression and drug resistance in a variety of malignant tumors." (PMID 36204178, 2022). "Overall, our study identified that the ferroptosis-related gene MT1G was significantly downregulated in the tumor tissues of ccRCC patients." (PMID 36204178, 2022). "The qRT‒PCR and Western blot results showed that MT1G expression in tumor tissues was downregulated compared with that in the corresponding para-cancer tissues of patients." (PMID 36204178, 2022). "The pan-cancer expression profiles of SLC7A11, HMOX1, and MT1G were subsequently analyzed by integrating tumor samples in TCGA with normal samples in GTEx using the rank-sum test." (PMID 35360452, 2021). "MT1G uncovered the capability of tumor suppressor via promoting CRC differentiation through zinc signaling." (PMID 32351322, 2020). "MT1G promotes new tumor suppressor activity in CRC tumor differentiation and indicates that MT and zinc signaling as new participants in colorectal differentiation." (PMID 33240582, 2020). "Some of the top DNA hypermethylated IRGs, such as BMP8B, PLA2R1, MSX1, DGCR5, and MT1G, were previously identified as tumor suppressors in gastric and other cancers." (PMID 32841292, 2020). "The authors uncovered that MT1G was involved in the process of tumor cell differentiation mainly through the Notch signaling pathway and labile zinc chelation and redistribution." (PMID 30139373, 2018). "Tumour-intrinsic determinants at least partially account for this heterogeneity, since we observed that human cancer cell lines and individual tumour explants present great differences in their induction of MT1G mRNA upon exposure to sorafenib." (PMID 27184800, 2016).
tumor (continued). "The tumours were prepared as thin slices and maintained for 18 h in the presence of sorafenib in order to examine its effect on MT1G mRNA expression levels." (PMID 27184800, 2016). "We examined the clinical relevance of our findings by analysing the regulation of MT1G in five tumour explants prepared from surgical HCC samples." (PMID 27184800, 2016). "Taken altogether, our results indicate that miR-1246 and miR-1290, which are enriched in TICs, have critical roles in regulating tumour growth and metastasis, in part, through the repression of metallothioneins, especially MT1G." (PMID 27325363, 2016). "Our data also showed that MT1G re-expression induced cell cycle arrest and apoptosis, further supporting its tumor suppressor function." (PMID 24098937, 2013). "The suppressory role of MT-1G was additionally confirmed in vivo in athymic nude mice, as K1 cells with MT-1G expression yielded reduced tumour growth as compared to control cells." (PMID 23273222, 2012). "The results showed that MT1G was highly expressed in tumor tissues compared with normal tissues." (PMID 38747739, 2024). "Above results revealed that MT1G overexpression increased the subcutaneous tumorigenic capacity of ccRCC 786-O cells compared to the control group, resulting in more tumors, increased tumor weight, and larger tumor volumes." (PMID 38906969, 2024). "Furthermore, MT1G was more highly expressed in metastatic tumor tissues than in primary tumor tissues." (PMID 38747739, 2024). "Moreover, several studies have indicated that the occurrence of ferroptosis in MSCs significantly impacts tumor progression, with MT1G emerging as a critical regulator of this process." (PMID 38747739, 2024). "In addition, MT1G expression is closely related to the immune microenvironment and is involved in tumor progression." (PMID 39359721, 2024). "In ccRCC, the relative upregulation of MT1G may lead to tumor progression to the advanced stage and resistance to sorafenib, which might contribute to the effect of MT1G on ferroptosis by regulating GSH consumption." (PMID 36204178, 2022). "MT1G has been reported to suppress tumor metastasis and promote cancer cells differentiation 7,8." (PMID 33537082, 2021). "Moreover, MT1G was frequently downregulated in PDAC tumor tissues (17/21) compared with the adjacent counterparts." (PMID 33537082, 2021). "The results suggested that the expression of MT1G in HCC tissues was significantly downregulated compared to the paired non-tumor tissues (p = 0.0006, paired t-test), which was consistent with The Cancer Genome Atlas (TCGA) data (p < 0.0001) and previous reports." (PMID 31732712, 2019). "The results showed the expression of MT1G significantly affected the tumor size (p = 0.005)." (PMID 31732712, 2019). "Next, an in vivo study was performed to verify that MT1G suppresses HCC tumor growth." (PMID 31732712, 2019). "Among them, MT1G was the one that changed most dramatically as the tumor grew larger." (PMID 31732712, 2019). "Meanwhile, less Ki-67 staining was observed in MT1G-overexpressed tumor tissues." (PMID 31732712, 2019). "Our results revealed that MT1G was significantly downregulated in tumor tissues, and could inhibit the proliferation as well as enhance the apoptosis of HCC cells." (PMID 31732712, 2019). "At the same time, tumor-suppressive genes such as MT1G, MT1M, CDKN1C, and DCN were overexpressed." (PMID 30568916, 2018). "In order to assess the independent association of MT1G hypermethylation with gender, age, tumor invasion, lymph node metastasis, tumor stage, and tumor recurrence, we further performed multivariate logistic regression." (PMID 24098937, 2013). "In addition to SPINT2, four further genes (CDH1, PLAU, IGFB3 and MT1G) had previously been reported to undergo promoter region hypermethylation in RCC tumours." (PMID 18195710, 2008).
tumor (continued). "Moreover, our subcutaneous tumor experiment in immunodeficiency mice revealed that MT1G knockdown markedly inhibits ccRCC growth, with a noticeable decrease in the number of lipid droplets in tumors formed by MT1G knockdown cells compared to the control group." (PMID 38906969, 2024). "Our in vivo assay further confirmed that MT1G could suppress HCC tumor growth in nude mice." (PMID 31732712, 2019). "As for MT1H and MT1G, it is known that metallothioneins (MTs) represent a class of proteins involved in processes of cellular detoxification from ROS and heavy metals and, through this mechanism, they might act as tumor-suppressor genes." (PMID 25945129, 2015). "MT1G (Metallothionein 1 G) and MT1H have the potential to suppress tumor growth and are regulated by DNA methylation in their promoter regions." (PMID 38609844, 2024). "Consistent with previous reports, the expression of ACSL4 and GPC3 was increased, and the expression of MT1G and SLC22A1 was decreased in the tumor tissues." (PMID 38188684, 2023). "SOSTDC1, TLR5, MT1G, and MUC6 were downregulated in locally advanced tumor tissue samples, whereas COL8A1 and THBS2 were upregulated (P<0.05)." (PMID 36969001, 2023). "Among these ten genes, the expression levels of SETD1B, ACSF2, MUC1, KLHL24, PML, MT1G, and GPT2 were higher in tumor tissues than those in normal tissues, while HIC1, AKR1C1, and LOC390705 were lower expressed in tumor tissues." (PMID 35071242, 2021). "For instance, upregulation of miR-1246 and miR-1290 led to repression of metallothioneins, especially metallothionein 1G (MT1G), which led to increased TIC ability to initiate tumor growth and metastasis in NSCLC." (PMID 32316322, 2020). "Interesting, 3 MT superfamily numbers, MT1M, MT1G and MT1P2 were significantly down-regulated in the HCC tumor tissues." (PMID 28380433, 2017). "A more than two-fold increase in MT1G mRNA upon exposure to sorafenib (10 μM, 18 h) was seen in two out of the five HCC tumours." (PMID 27184800, 2016). "Thus, our study unveils the novel MT1G/H3K14me3/CPT1B signaling axis, which drives lipid accumulation in ccRCC, promoting ccRCC tumor growth and metastasis." (PMID 38906969, 2024). "Moreover, tumor cells showed lower expression of the metallothionein family genes, including MT1H and MT1G." (PMID 35974387, 2022). "Furthermore, we observed a similar trend of mRNA expression of TRAF7 and MT1G in PDAC clinical samples, in which both of MT1G and TRAF7 were down-regulated in tumor tissues compared with the adjacent counterparts." (PMID 33537082, 2021). "All these reports seemingly indicated that MT1G was a candidate tumor suppressor in HCC, however, which has never been investigated before our study." (PMID 31732712, 2019). "The linear regression analysis also revealed a significant negative correlation between the tumor size and the expression of MT1G (p = 0.046, R2 = 0.0821)." (PMID 31732712, 2019). "Second, in a cohort of NSCLC patients with paired tumour and normal tissues (n=9), MT1G was strongly expressed in normal tissues but markedly reduced in tumours." (PMID 27325363, 2016). "To further test whether MT1G controls metastasis independent of tumour size, we introduced MT1G-expressing tumourspheres or control cells directly into the lung through tail-vein injection." (PMID 27325363, 2016). "While we identified the putative tumour suppressor, MT1G, as a common target for miR-1246 and miR-1290, one could not exclude the possibility that other miRNA target genes could also contribute towards the inhibition of tumorigenicity." (PMID 27325363, 2016). "Notably, MT1G could not be simply identified as a tumor suppressor gene or oncogenic gene in ccRCC, but MT1G seemed to play a dual role in the development and progression of tumors." (PMID 36204178, 2022).
tumor (continued). "Moreover, we analyzed the correlation among four-gene signature (FeSig) (BID, TAZ, MT1G, and SLC7A11), downstream hub genes (CPNE7, WNT10B, ADAMTS14, and RUFY4), and immune checkpoints (PD-1, CTLA4, LAG3, and TIGIT) to further discover potential molecular mechanisms of tumor immunity." (PMID 34367965, 2021). "Negative correlation between MT1G and INHBA was also observed in PDAC clinical samples, in which MT1G was down-regulated while INHBA was up-regulated in tumor tissues compared with the adjacent counterparts." (PMID 33537082, 2021). "In normal kidney tissue ANKS1B, ACOT6, EYS, CHRNA6, MT1G and UTY were up regulated in smokers in comparison to non-smokers; however, these genes tended to be down regulated in smokers versus non-smokers in ccRCC tumor tissue." (PMID 24479813, 2014).
cancer (40 papers, 2007 to 2025). A tumor composed of atypical neoplastic, often pleomorphic cells that invade other tissues. "In the context of cancer, particularly HCC, the upregulation of MT1G has been linked to resistance against sorafenib, a kinase inhibitor commonly used in cancer therapy." (PMID 39534872, 2024). "5-Aza-dC treatment only caused partial reactivation of MT1G in most of cancer cell lines." (PMID 24098937, 2013). "CDKN1A, EMC2, FDFT1, HSPB1, and MT1G were assessed for their ability to serve as prognostic indicators in pan-cancer by utilizing the TCGA database." (PMID 40432442, 2025). "Sucralose 6-acetate was shown to significantly increase the expression of genes related to inflammation, oxidative stress, and cancer, with the highest expression observed for the metallothionein 1 G gene (MT1G)." (PMID 40005309, 2025). "The mRNA levels of CDKN1A, EMC2, FDFT1, HSPB, and MT1G, were analyzed comprehensively, and any correlations between the levels of mRNA of these five genes and pan-cancer prognosis were identified." (PMID 40432442, 2025). "The expression of mRNA of CDKN1A, EMC2, FDFT1, HSPB1, and MT1G in the TCGA and GTEx datasets were evaluated through the analysis of pan-cancer." (PMID 40432442, 2025). "Here, we found that miR-1290 directly transferred from high-metastatic cancer cells to NFs via EVs, and further activate NFs to CAFs through MT1G/AKT pathway." (PMID 38825680, 2024). "Immunofluorescence results further supported a decrease in MT1G protein expression in ccRCC cancer patients." (PMID 38906969, 2024). "MT1G expression significantly correlates with advanced cancer stage and grade, both at the protein and mRNA levels." (PMID 38906969, 2024). "To investigate the role of MT1G in ccRCC cancer development, we conducted cell function experiments using ccRCC 786-O and A498 cell lines." (PMID 38906969, 2024). "Analysis of the TCGA database revealed that the MT1G gene exhibits reduced expression in ccRCC cancer." (PMID 38906969, 2024). "In the study of drug-resistant cancer cells, it is found that the target gene of metallothioneins-1G (MT-1G) is a biomarker and contributing factor of sorafenib resistance." (PMID 34996454, 2022). "MT1G is a DNA methylation-related gene which is reported to play an important role in various types of cancer." (PMID 35167648, 2022). "As MT1G was hypermethylated in resistant cells, we were interested in the possibility of ROS re-expressing MT1G of cancer stem cells through demethylation." (PMID 33537082, 2021). "Sphere formation assay showed that the sphero-forming ability, a trait of in vitro cancer stemness, was enhanced in MT1G knockdown cells." (PMID 33537082, 2021). "Downregulation of MT1G conferred to enhanced cancer stemness properties in chemoresistant PDAC cells." (PMID 33537082, 2021). "To understand how MT1G represses cancer stemness, we performed secretome analysis and found that nuclear factor kappa B (NF-κB) pathway was enriched." (PMID 33537082, 2021). "Conversely, overexpression of MT1G in gemcitabine resistant PDAC cells led to the loss of cancer stemness properties as shown by decreased cell markers expressions, sphere formation ability and cells' viability in response to gemcitabine." (PMID 33537082, 2021). "The findings demonstrated a NRF2-dependent regulation of the transcription of the MT1G gene in cancer cells exposed to sorafenib." (PMID 27184800, 2016). "Compared with 5-Aza-dC treatment alone, MT1G expression was more significantly restored in these cancer cells treated with SAHA alone or in combination with 5-Aza-dC." (PMID 24098937, 2013). "For K1 cells, there was a significantly lower number of migrated cells in MT1G-transfected cells than empty vector-transfected cells (P <0.01), indicating that MT1G inhibited cancer cell migration." (PMID 24098937, 2013).